CSNK1E (casein kinase 1 epsilon)
Diseases named in the same sentence as CSNK1E in open-access papers (continued):
Sharing a sentence is not in itself a finding about the gene and the disease.
neuroblastoma (1 paper, 2025). Neuroblastoma (NB) is the most common solid, extracranial childhood tumor. "We next repeated the TDP-43 IP-qPCR assays in the nuclear extracts of SH-SY5Y neuroblastoma cells treated with MPP+ in triplicate and found that TDP-43 binding to MALAT1 was significantly increased, while TDP-43 binding to the 3′ UTR of SLC1A5, CSNK1E, and HMGB2 mRNAs was significantly decreased." (PMID 39837396, 2025).
Obesity (1 paper, 2024). Accumulation of substantial excess body fat. "Our study identified three key circadian genes (BHLHE40, PPP1CB, and CSNK1E) associated with obesity." (PMID 39351493, 2024). "Abnormal expressions of PPP1CB and CSNK1E in obesity directly affect the core clock genes (PER1, PER2), and the accumulation of PERs and CRYs in the nucleus inhibits the transcription of CLOCK and BMAL1, disrupting energy homeostasis and leading to obesity." (PMID 39351493, 2024). "PPP1CB can dephosphorylate CSNK1E, suggesting that these two genes may contribute to the immune landscape in obesity collectively." (PMID 39351493, 2024). "Lower expression of CSNK1E could accelerate obesity-related inflammation." (PMID 39351493, 2024). "The expressions of CSNK1E (OR: 0.922, 95% CI: 0.853–0.997, p = 0.043) and PPP1CB (OR: 0.958; 95% CI: 0.922–0.995; p = 0.027) may be associated with a lower risk of obesity, while BHLHE40 (OR: 1.093, 95% CI: 1.010–1.183, p = 0.0028) may be associated with a higher risk of obesity." (PMID 39351493, 2024). "Our research findings suggest that the circadian genes (BHLHE40, CSNK1E, and PPP1CB) could serve as novel biomarkers for understanding the pathogenesis of obesity." (PMID 39351493, 2024). "In conclusion, the key circadian genes (BHLHE40, CSNK1E, and PPP1CB) may serve as novel biomarkers for understanding obesity pathogenesis and have significant correlations with infiltrating immune cells, thus providing potential new targets for obese prevention and treatment." (PMID 39351493, 2024).
pancreatic adenocarcinoma (1 paper, 2012). "CKIε is a protein product of the CSNK1E gene and has been shown to be important in regulating cell division and tumour growth in human pancreatic adenocarcinoma and salivary gland cancer by phosphorylating key proteins in the Wnt signalling pathway." (PMID 22707389, 2012).
renal carcinoma (1 paper, 2022). A carcinoma arising from the epithelium of the renal parenchyma or the renal pelvis. "Immunohistochemical staining results of the bioinformatics analysis showed that the protein levels of GNA11 and THRAP3 were significantly decreased in renal cancer tissues, and the protein levels of CSNK1E did not change significantly." (PMID 35877357, 2022).
cancer (22 papers, 2008 to 2025). A tumor composed of atypical neoplastic, often pleomorphic cells that invade other tissues. "In particular, we found the presence of transcripts, such as Cux1 and Arpc2, which variably regulate DNA replication, cell proliferation and motility and Csnk1e, which is implicated in the Wnt/β-catenin pathway, a key determinant in cancer proliferation." (PMID 39061080, 2024). "For instance, previous investigations have demonstrated that loss of HMGCR, CDK9, ARK5, or CSNK1e gene is highly detrimental for the survival of cancer cells exhibiting c-Myc activation." (PMID 29207593, 2017). "Additionally, we investigated the relationship between CSNK1E expression and prognosis across the 33 cancer types, identifying it as a risk factor in 12 of them, including ACC and BLCA." (PMID 39872053, 2024). "Casein kinase 1 epsilon (CK1ε) plays a central role in oncogenic signaling pathways and is a promising but understudied target in cancer therapy." (PMID 40430559, 2025). "This suggests that silencing CSNK1E can reverse the TGF-β1-induced migration in cancer cells, implying a potential synergistic role of CSNK1E in TGF-β1-related pathways." (PMID 39872053, 2024). "We conducted a pan-cancer analysis of CSNK1E across 33 different cancer types, comparing its expression levels in tumor versus normal groups." (PMID 39872053, 2024). "Pan-cancer analysis further revealed heterogeneous expression patterns and prognostic potential of CSNK1E across various cancers." (PMID 39872053, 2024). "Casein kinase 1 epsilon (CK1ε) gene expression plays a role in numerous cancers, and the knockdown of CK1ε induces tumor cell-selective cytotoxicity." (PMID 31602258, 2019). "We showed that PER1, PER2, and PER3 gene expression levels were all lower in cancer tissue than in liver tissue, while CSNK1E gene expression was higher in cancer tissue." (PMID 27492458, 2016). "Recent studies have indicated that casein kinase 1-epsilon (CK1ɛ) and casein kinase 1-delta (CK1δ) expression has a role in human cancers." (PMID 24557581, 2014). "CSNK1E was also identified as an essential gene in cancer cell lines from multiple tumor types in addition to breast, including colon, prostate, and brain (data not shown), as well as other cancer cell lines in previously published reports." (PMID 20126544, 2010). "Treatment with IC261, a kinase domain inhibitor of casein kinase 1-epsilon (CK1ε), a protein product of CSNK1E, showed a similar degree of cancer-cell-selective growth inhibition." (PMID 18518968, 2008). "More importantly, depletion of PRRC2A or CSNK1E suppressed the stemness of cancer cells and tumor growth, suggesting that this regulatory machinery could be of therapeutic interest for CRC." (PMID 39582289, 2025). "Finally, we performed a pan-cancer analysis of the CSNK1E gene, investigating its expression across various cancers and its prognostic implications, as well as its co-expression with EMT-related genes." (PMID 39872053, 2024). "Finally, a pan-cancer analysis of CSNK1E was conducted, and we explored the co-expression of EMT-related genes." (PMID 39872053, 2024). "Taken together, these data suggest that CSNK1E is not only required for cancer cell proliferation and transformation in the context of activated β-catenin, but can also promote transformation, potentially through activation of the Wnt/β-catenin signaling pathway." (PMID 20126544, 2010). "We found that CSNK1E is one such target gene upon which cancer cells depend more than normal cells." (PMID 18518968, 2008). "In addition to the identification of CSNK1E as a novel cancer-relevant gene, these observations demonstrate the power of integrating complementary unbiased functional genomic approaches to identify genes involved in specific cancer pathways." (PMID 20126544, 2010).
cancer (continued). "CSNK1E was overexpressed in several cancer tissue samples and compared to non-tumorigenic normal tissue, suggesting a positive role of CSNK1E in neogenesis or maintenance." (PMID 35393513, 2022). "Casein Kinase 1 epsilon (CK1ε) is a member of the serine (Ser)/threonine (Thr) CK1 family, known to have crucial roles in several biological scenarios and, ever more frequently, in pathological contexts, such as cancer." (PMID 32899434, 2020). "Primary or subgroup meta-analysis for the SNPs concerning all the other clock genes (ARNTL, CRY1, CSNK1E, NR1D1, TIMELESS) considered in this study were found to be not statistically significantly associated with cancer risk." (PMID 28177907, 2017). "Analysis of gene-expression data revealed that CSNK1E is overexpressed in several cancer tissue samples examined compared to non-tumorigenic normal tissue, suggesting a positive role of CSNK1E in neogenesis or maintenance." (PMID 18518968, 2008). "Functions of the remaining genes - including CSNK1E, FOSL1, PPP2R1A, and PPARD – are widely reported as being relevant to cancer (if not specifically NSCLC) biology." (PMID 33027769, 2020). "The roles of CSNK1E and MINK1 in a variety of cancers have not yet been investigated." (PMID 33818013, 2021). "Interestingly, the low rather than high levels of CSNK1E, IGF2R, IRAK3, and PRKAA1 relate to poor cancer prognosis, suggesting that kinases often play a divergent role in different types of cancer." (PMID 26956052, 2016).
tumor (18 papers, 2007 to 2025). "We report that knocking down CSNK1E, a clock gene encoding casein kinase 1-epsilon (CK1ε), induces tumor-cell-selective cytotoxicity." (PMID 18518968, 2008). "Our findings revealed that, with the exception of GLI2 and CSNK1E, the majority of these prognostic‐related HRGs exhibited elevated levels of methylation within tumor tissues." (PMID 41427028, 2025). "According to the results from Western blot assays, CSNK1E is expressed in both normal and tumor tissues, with significantly higher levels in tumor samples." (PMID 39872053, 2024). "CSNK1E, a clock gene that controls circadian rhythms, has been shown to suppress tumor cell development selectively." (PMID 35368886, 2022). "In the absence of PER2, Myc levels greatly rise, thereby explaining why many types of tumours display higher levels of CSNK1E than their normal cell equivalents." (PMID 27465361, 2016). "The casein kinases CSNK1A1L and CSNK1E were down-regulated in neighbouring mucosa and up-regulated in tumour tissue, while CSNK1A1 was down-regulated in both tissue types." (PMID 27465361, 2016). "Furthermore, tumor xenograft assay also demonstrated that CSNK1E overexpression reversed the inhibitory effect of PRRC2A knockdown on tumor growth." (PMID 39582289, 2025). "We employed a two-step screening strategy using human sarcoma cell lines and human fibroblast-derived isogenic cell lines, and found that short hairpin RNAs targeting CSNK1E, a clock gene that regulates circadian rhythms, can induce selective growth inhibition in engineered tumor cells." (PMID 18518968, 2008). "We found that ROR1 could interact with casein kinase 1 epsilon (CK1ε) to activate phosphoinositide 3-kinase-mediated AKT phosphorylation and cAMP-response-element-binding protein (CREB), which was associated with enhanced tumor-cell growth." (PMID 22403610, 2012). "Nonetheless, there is a notable absence of literature on the role of CSNK1E in MM at present, highlighting the need for further research into its functions in tumor biology." (PMID 39872053, 2024). "Notably, CSNK1E and RAC3 demonstrated a significant correlation with EMT, indicating their potential involvement in mediating the metastatic process of MM cells, as EMT facilitates tumor cell invasion through the basement membrane into the bloodstream." (PMID 39872053, 2024). "In addition, reverse transcription polymerase chain reaction (RT-PCR) analysis of these tumor samples revealed that the MS67 treatment led to down-regulation of WDR5 target genes such as ribosome subunits and oncogenesis-related transcripts including BCL2 and CSNK1E." (PMID 34586829, 2021).
hematological malignancies (1 paper, 2021). "Other relevant PI3K inhibitors with FDA approval to treat hematological malignancies include the pan-PI3K inhibitor with preferential activity towards PI3K-α/-δ copanlisib, the PI3K-γ/-δ inhibitor duvelisib and the recently approved PI3K-δ/Casein kinase 1 epsilon (CSNK1E) inhibitor umbralisib." (PMID 34683897, 2021).
CSNK1E also shares sentences with these, for which no sentence is quoted: colorectal cancer (3 papers); colon cancer (2); depression (2); schizophrenia (2); acute myeloid leukemia (1); adrenocortical carcinoma (1); arthropathy (1); breast tumor (1); clear cell renal cell carcinoma (1); epilepsy (1); Familial advanced sleep-phase syndrome (1); follicular lymphoma (1); Hepatic fibrosis (1); heroin addiction (1); lung carcinoma (1); Mcc (1); mesothelioma (1); mood disorder (1); mucopolysaccharidosis type 2 (1); myoclonic epilepsy (1); myotonic dystrophy (1); neurodegenerative disease (1); neurodevelopmental disorder (1); neurological diseases (1); oral cancer (1); oral squamous cell carcinoma (1); pancreas cancer (1); primary immunodeficiency (1); Progressive myoclonic epilepsy (1); rectal cancer (1).
A further 3 diseases each share a sentence with CSNK1E in 1 paper.